MAMLD1 (mastermind like domain containing 1)
Diseases named in the same sentence as MAMLD1 in open-access papers:
MAMLD1 is named in the same sentence as 41 diseases in open-access papers, as found by Europe PMC text mining. Sharing a sentence is not in itself a finding about the gene and the disease. The quoted sentences say what the papers report.
hypospadias (27 papers, 2011 to 2025). Hypospadias is the displacement of the urethral meatus on the ventrum of the penis. "Studies of such patients described mutations in other genes crucial for sexual development, such as the hypospadias-associated MAMLD1 gene or the FKBP4 gene, encoding a regulator of the AR signaling pathway." (PMID 40247401, 2025). "We found MAMLD1 p.N662S variant in two patients with isolated hypospadias, which were also identified by other hypospadias mutation studies." (PMID 34276780, 2021). "Third, apart from the previously reported MAMLD1 variants, the effect of the novel MAMLD1 variants in our cohort on the development of hypospadias needs to be confirmed by further functional genetic studies." (PMID 32690052, 2020). "To date, approximately 20 MAMLD1 sequence variations have been documented in the Human Gene Mutation Database and described in patients who have 46,XY DSDs, mostly presenting with hypospadias." (PMID 32690052, 2020). "Hypospadias is a relatively common abnormality in children, affecting approximately 1/150 newborn males, and is associated with the MAMLD1 (Xp28) and ATF3 (1p32.3) genes for 46,XY-isolated hypospadias." (PMID 33158283, 2020). "The core anomaly in patients with MAMLD1 variants are hypospadias, but ambiguous genitalia, cryptorchidism, micropenis and female external genitalia with complete gonadal dysgenesis have also been observed." (PMID 31719618, 2019). "To date, pathogenic mutations of MAMLD1 have been identified primarily in infants or prepubertal boys with hypospadias." (PMID 28629181, 2017). "MAMLD1 mutations, which are presumed to affect androgen biosynthesis in the fetal testis, result in hypospadias." (PMID 28629181, 2017). "Nevertheless, analyses of large case-control studies revealed the double S-S haplotype including MAMLD1 P359S and N662S as a risk factor for hypospadias." (PMID 26580071, 2015). "Mutations in the mastermind-like domain-containing 1 (MAMLD1) gene have been implicated as one of the causes of hypospadias in children." (PMID 23272655, 2012). "We present the case of a 35-day-old male Egyptian baby who presented with X-linked congenital adrenal hypoplasia due to a DAX-1 mutation associated with hypospadias due to a mutation of MAMLD1." (PMID 23272655, 2012). "Polymorphisms of MAMLD1 have been reported in patients with isolated hypospadias, the less severe form of 46,XY DSD, but these variants usually do not affect the transactivation of the protein." (PMID 22479329, 2012). "We and others have found that the S-S haplotype is associated with a minor form of DSD, i.e., isolated hypospadias, but the in vitro functional study of the p.P359S-p.N662S MAMLD1 variant was inconclusive with unchanged transactivation function." (PMID 22479329, 2012). "We identified two new mutations of MAMLD1 in patients with severe hypospadias and microphallus (1 stop codon and 1 missense mutation)." (PMID 22479329, 2012). "MAMLD1 (mastermind-like domain containing 1, alias CXorf6) on human chromosome Xq28 is a causative gene for hypospadias, a mild form of 46,XY disorders of sex development (DSD)." (PMID 21559465, 2011). "This is consistent with previous reports indicating that mutations involving MAMLD1 are rare in hypospadias." (PMID 22028768, 2011). "Although previous studies have indicated that MAMLD1 mutations result in hypospadias primarily because of compromised testosterone production around the critical period for fetal sex development, the underlying mechanism(s) remains to be clarified." (PMID 21559465, 2011). "We hypothesize that the expression of this truncated protein driven by the MAMLD1 regulatory region (which is expressed in the developing genitalia) results in a gain-of-function causing hypospadias in this patient." (PMID 40597352, 2025). "Several studies have reported the involvement of MAMLD1 polymorphisms in hypospadias patients." (PMID 32690052, 2020).
hypospadias (continued). "Overall, the genes detected in our eight studied patients with MAMLD1 variants have been previously reported in humans with hypospadias, cryptorchidism, micropenis, and other urogenital abnormalities; or they have been found involved in sexual and gonadal development." (PMID 31555317, 2019). "MAMLD1 on the human X chromosome is a causative gene for hypospadias." (PMID 28629181, 2017). "Further, mutation c.325delG in the MAMLD1 gene was detected, which may point to a possible etiology of hypospadias in our patient’s case." (PMID 23272655, 2012). "In addition, several genes, such as SRY type HMG box9 (SOX9), HomeoboxA13 (HOXA13), Wilms tumor 1 (WT1) and mastermind-like domain-containing 1 (MAMLD1) are reported to be associated with hypospadias." (PMID 23272655, 2012). "Variants in the MAMLD1 gene have been associated with a broad range of DSD phenotypes, mainly hypospadias." (PMID 38962685, 2024). "KK-LC-1/CT83/ CXorf6/MAMLD1 was found to be a critical gene in hypospadias and plays a less important role in testosterone production during the critical time for sex development." (PMID 34359776, 2021). "Mamld1 has been demonstrated to be related to testosterone production in MLTC1 cells, and has been found to be a causative gene in inordinate of sex development (DSDs) with hypospadias as a salient clinical phenotype." (PMID 33581723, 2021). "Regarding the minor forms of 46,XY DSD with isolated and non-severe hypospadias, mutational studies of MAMLD1 have identified several polymorphisms in this gene." (PMID 22479329, 2012). "The MAMLD1 gene on Xp28 was sequenced in 55 of the cases with ambiguous genitalia or hypospadias." (PMID 22028768, 2011). "We did not identify mutations in the MAMLD1 gene in a screen of 55 of the ambiguous genitalia/hypospadias cases." (PMID 22028768, 2011). "Meanwhile, 20 MAMLD1 sequence variations have been described in patients who have a 46,XY disorder of sex development (DSD), mostly presenting with hypospadias." (PMID 26580071, 2015). "Polymorphisms, mutations, and epigenetic changes in the AR, CYR61, HSD17B3, HSD3B1, MAMLD1, SRD5A2, and STARD3 have been associated to hypospadias risk in severe types of hypospadias that have not been found in mild hypospadias." (PMID 33425810, 2020). "Although Mamld1 KO mice exhibited no hypospadias, phenotypic differences between human patients and KO mice can be explained by inter-species differences in steroid metabolism." (PMID 28629181, 2017). "Mamld1 KO male mice were viable and exhibited no hypospadias." (PMID 28629181, 2017).
ependymoma (11 papers, 2019 to 2024). A WHO grade II, slow growing tumor of children and young adults, usually located intraventricularly. "YAP1::MAMLD1 gene fusions define one subtype of supratentorial ependymoma while ZFTA fusions define a more aggressive subtype." (PMID 40491864, 2024). "Supporting this argument, addition of the IDR of MAMLD1 to constitutively nuclear YAP was sufficient to result in ependymoma." (PMID 40491864, 2024). "YAP1 at 11q22.1, encoding for a DNA-binding Hippo pathway regulatory protein, and MAMLD1 fusions (YAP1-MAMLD1) appear to drive oncogenesis in a subset of supratentorial ependymomas occurring mostly in female infants." (PMID 36604386, 2023). "In the ependymoma cells, the chimeric TFs YAP-mastermind-like domain-containing 1 (MAMLD1) and zinc finger translocation-associated (ZFTA/C11ORF95)-YAP form nuclear condensates and substantially reconfigure spatial genomic contacts as revealed by HiChIP analysis." (PMID 39684613, 2024). "In addition, certain tumors exhibit aberrant YAP fusion events, such as YAP—mastermind-like domain-containing protein 1 (MAMLD1) and C11ORF95-YAP in ependymomas." (PMID 38067201, 2023). "A recent fascinating study found that the fusion proteins YAP::MAMLD1 and ZFTA::YAP but not wild-type YAP undergo LLPS in ependymoma that is critical to their oncogenesis." (PMID 40491864, 2024).
cryptorchidism (6 papers, 2019 to 2025). The failure of one or both testes of a male fetus to descend from the abdomen into the scrotum during the late part of pregnancy. "It is after cryptorchidism the second most common human birth defect of the male genitalia, detected once every 330 male births and up to now in humans, only three nonsense mutations within the mastermind-like domain containing 1 (MAMLD1) gene have been correlated to it." (PMID 31923267, 2020). "The other phenotypes included cryptorchidism, bifid scrotum, and/or micropenis, which is consistent with the phenotypes of previously documented patients with MAMLD1-related DSDs." (PMID 32690052, 2020). "The seven MAMLD1 patients with 46,XY DSD presented phenotypes from female external genitalia (patient 4) to variable degrees of hypospadias, cryptorchidism and small penis." (PMID 31555317, 2019).
disorders of sex development (4 papers, 2011 to 2021). "Mastermind-like domain-containing 1 (MAMLD1) has previously been identified as a causative gene for “46,XY Disorders of Sex Development (DSD)”." (PMID 32690052, 2020). "Mastermind-like domain-containing 1 (MAMLD1) has been shown to play an important role in the process of sexual development and is associated with 46,XY disorders of sex development (DSDs)." (PMID 33424767, 2020).
myotubular myopathy (4 papers, 2015 to 2024). "The MAMLD1 (mastermind-like domain-containing 1, previously also known as CXorf6) gene (OMIM 300120) has been first identified in a patient with myotubular myopathy and male hypogenitalism who was found to harbor a deletion on chromosome Xq28." (PMID 26580071, 2015). "Mastermind-like domain-containing 1 gene (MAMLD1), also known as chromosome X open reading frame 6 (CXorf6) or F18 (online Mendelian inheritance in man (OMIM)# 300120), was first reported in two cases of myotubular myopathy and male hypogenitalism." (PMID 33424767, 2020). "Mastermind-like domain-containing 1 gene (MAMLD1), also known as chromosome X open reading frame 6 (CXorf6) or F18 (OMIM# 300120), was first identified in two patients with myotubular myopathy and male hypogenitalism, who were discovered to possess a deletion on chromosome Xq28." (PMID 38962685, 2024). "The mastermind-like domain-containing 1(MAMLD1) gene, previously known as Chromosome X open reading frame 6 (CXorf6) or F18 (OMIM# 300120), was first identified in two patients with myotubular myopathy and male hypogenitalism, who were found to harbour a deletion on chromosome Xq28." (PMID 32690052, 2020).
androgen excess (2 papers, 2019 to 2021). "CpG hypomethylation in genes such as AKR1C3, GHRHR, MAMLD1 and RETN, and hypermethylation in TNF, which can indirectly contribute to androgen excess, were consistent with increased and decreased levels of the respective gene transcripts." (PMID 30975191, 2019). "Recent research has shown that CpG hypomethylation regarding GHRHR, AKR1C3, RETN, and MAMLD1 and hypermethylation regarding TNF, which can indirectly contribute to androgen excess, were consistent with increased and decreased levels of the corresponding gene transcripts, respectively." (PMID 33763111, 2021).
anorchia (2 papers, 2011 to 2016). "We evaluated the clinical and biological presentation, and family histories of 26 boys with anorchia, and sequenced their SRY, NR5A1, INSL3, MAMLD1 genes and the T222P variant for LGR8." (PMID 21853106, 2011). "All patients with anorchia were sequenced for SRY, NR5A1, INSL3, MAMLD1 and the T222P variant of LGR8 and no pathogenic mutations were identified." (PMID 27899089, 2016).
brain tumor (2 papers, 2020 to 2024). "In vivo, mutation of the TEAD binding site of YAP in YAP::MAML2, YAP::MAMLD1, YAP::FAM118B, YAP::SS18, and YAP::TFE3 significantly reduced the oncogenic potential of these protein fusions to initiate brain tumors in mice." (PMID 40491864, 2024). "Mouse brain tumors formed from YAP::FAM118B, YAP::MAMLD1, or YAP::SS18 fusion protein expression showed distinct morphology and gene expressions profiles from brain tumors with the YAP::TFE3 fusion protein." (PMID 40491864, 2024). "Working in vivo, multiple studies demonstrated that several YAP fusion proteins, such as YAP::FAM118B, YAP::MAML2, YAP::MAMLD1, YAP::SS18, and YAP::TFE3, can induce brain tumors and/or muscle tumors in mice." (PMID 40491864, 2024).
ovarian dysfunction (2 papers, 2019 to 2023). The inability of the ovaries to function. "MAMLD1 (mastermind-like domain containing 1) has been associated with disorders of sex development in men, as well with ovarian dysfunction in women." (PMID 37337145, 2023). "We therefore performed whole exome sequencing (WES) in seven of these 46,XY patients with DSD and in one 46,XX patient with ovarian insufficiency, who all carried MAMLD1 variants." (PMID 31555317, 2019). "Therefore, in this study, we performed WES in seven 46,XY patients with DSD and one 46,XX patient with ovarian insufficiency, who all carried MAMLD1 variants." (PMID 31555317, 2019).
adrenal hypoplasia (1 paper, 2012). "We report the case of a male Egyptian baby with an association of congenital adrenal hypoplasia due to a DAX-1 mutation and hypospadias due to mutation of the MAMLD1 gene." (PMID 23272655, 2012). "We report the case of an Egyptian baby with an association of congenital adrenal hypoplasia due to DAX-1 mutation and hypospadias due to MAMLD1 mutation." (PMID 23272655, 2012).
astroblastoma (1 paper, 2023). "In decreasing order of frequency, EWSR1, MN1, and MAMLD1 are the reported fusion partners of BEND2 in astroblastoma-like gliomas." (PMID 36690805, 2023).
cardiac arrhythmia (1 paper, 2020). Any disturbances of the normal rhythmic beating of the heart or MYOCARDIAL CONTRACTION. "MAMLD1 gene, included in the Notch signaling pathways, was the only one ranked as important for predicting cardiac arrhythmias by both selection procedures." (PMID 32508633, 2020).
congenital adrenal hypoplasia (1 paper, 2012). "A molecular genetics study confirmed the diagnosis of X-linked congenital adrenal hypoplasia due to DAX-1 mutations and hypospadias due to MAMLD1 mutation." (PMID 23272655, 2012).
epithelial tumors of the skin (1 paper, 2013). "The Mamld1 gene has been mutated by insertions in epithelial tumors of the skin (tumor 01, 02, and 03)." (PMID 23940809, 2013).
gonadal dysgenesis (1 paper, 2024). A congenital disorder characterized by the presence of extremely hypoplastic gonads preventing the development of secondary sex characteristics. "Based on our literature review, this is the first case with the combined presence of pathogenic mutations in the MAMLD1 gene and DHX37 gene in a patient with gonadal dysgenesis." (PMID 38962685, 2024).
Hypergonadotropic hypogonadism (1 paper, 2017). Reduced function of the gonads (testes in males or ovaries in females) associated with excess pituitary gonadotropin secretion and resulting in delayed sexual development and growth delay. "Although three patients with MAMLD1 mutations were reported to have hypergonadotropic hypogonadism in their teens, the functional significance of MAMLD1 in the postnatal testis remains unclear." (PMID 28629181, 2017).
hypogonadotropic hypogonadism (1 paper, 2015). Abnormal ovarian or testicular function due to insufficient hormonal stimulation from the hypothalamic-pituitary axis. "Remarkably, this patient also presented with hypogonadotropic hypogonadism at pubertal age suggesting that MAMLD1 may also be involved in the HPG axis, what has not been described so far, or that the patient may harbor additional genetic defects." (PMID 26580071, 2015).
male infertility (1 paper, 2024). The inability of the male to effect fertilization of an ovum after a specified period of unprotected intercourse. "For example, we reported rs927968522 (MAFALFA = 2.10E−04), which mapped in the Mastermind Like Domain Containing 1 (MAMLD1) gene (a locus with ‘strong’ evidence of contributing to male infertility according to IMIGC) and encoded an amino acid change (Pro > Leu) in residue 384 of the protein." (PMID 39678461, 2024). "We have also identified putatively causal variants in seven genes validated as aetiological factors of male infertility, such as SPAG17, REC114, TERB1, DNAH6, ADGRG2, MAMLD1, and USP26." (PMID 39678461, 2024).
Obesity (1 paper, 2024). Accumulation of substantial excess body fat. "In addition, MAMLD1 is one of the candidate genes for early-onset obesity, linking the genetic basis of obesity with reduced reproductive performance." (PMID 38483771, 2024).
skin tumors (1 paper, 2021). "Insertions into Zmiz1 and Mamld1 have been previously observed in skin tumors induced by transposon insertional mutagenesis." (PMID 34398873, 2021).
tumor (8 papers, 2013 to 2024). "Here the authors show that a YAP1- MAMLD1 fusion drives tumor formation in mice and show that the fusion protein can collaborate with the TEAD and NFI transcription factors." (PMID 31477715, 2019). "Among the candidate cancer genes defined by clonal expansion, two genes were hit independently at different TTAA sites in multiple tumors (excluding genes shared by tumor 05 and 09, which share a common origin): Mastermind-domain like 1 (Mamld1) and Diacylglycerolkinase delta (Dgkd)." (PMID 23940809, 2013). "IHC revealed MAMLD1 to be positively (3+) expressed in the nucleus of ACTH-secreting tumor cells of human corticotroph PA (22/31, 70.9%), but absent in healthy human pituitary glands." (PMID 34517852, 2021). "Electroporation of YAP1-MAMLD1(L103P) did not attenuate the YAP1-MAMLD1-mediated tumor formation (n = 5/5, median survival: 31.5 days), suggesting that MAMLD1 transactivation function for Notch signaling may not be relevant to the YAP1-MAMLD1 oncogenic capacity." (PMID 31477715, 2019).
cancer (4 papers, 2013 to 2021). A tumor composed of atypical neoplastic, often pleomorphic cells that invade other tissues. "The involved fusion partners YES-associated protein 1 (Yap1) and mastermind-like domain containing 1 (Mamld1) are involved in several pathways, e.g., Hippo signaling pathway and Wnt/β-catenin pathway, active in various cancers." (PMID 34008056, 2021). "Thus, Mamld1 is a novel candidate cancer gene as a regulator of Notch signaling for epithelial tumors." (PMID 23940809, 2013).
MAMLD1 also shares sentences with these, for which no sentence is quoted: infection (4 papers); Micropenis (4); colibacillosis (2); congenital hypogonadotropic hypogonadism (1); Diarrhea (1); Ellis-van Creveld syndrome (1); Fraser syndrome (1); glioma (1); Mayer-Rokitansky-Küster-Hauser syndrome (1); Microphallus (1); Noonan syndrome (1); Onset (1); Penile hypospadias (1); premature ovarian failure (1); subependymoma (1); supratentorial ependymoma (1); thyroid cancer (1); thyroid tumor (1); type 2 diabetes mellitus (1).